CD163 (CD163 molecule)
Diseases named in the same sentence as CD163 in open-access papers (continued):
Sharing a sentence is not in itself a finding about the gene and the disease.
tumor (continued). "They showed that Tim-4+CD163+ resident macrophages in the omentum contributed to the acquisition of a cancer stem cell (CSC)-like phenotype in tumor cells and increased the tumor cell number in the ascites without affecting tumor development in the omentum." (PMID 37180125, 2023). "In both contexts, the majority of F4/80‐positive cells infiltrating the tumour were negative for both CD68 and CD163." (PMID 35924447, 2023). "Expression of CD163 (-) and CD206 (+-) was almost absent in the subcutaneous tumor tissue of NSG mice implanted with RBE cells." (PMID 37809069, 2023). "Regardless of the tumor-dominant group or the TME-dominant group, the abundance of CD163+ M2 macrophages was significantly enriched in the high ImmuneScore subgroup compared to the low ImmuneScore subgroup (P < 0.001)." (PMID 37821959, 2023). "The tumor microenvironment showed the presence of CD4+ T cells (86%); CD8+ T cells (27%); CD20+ B (67%); CD15+ cells (86%); and CD163+ M2 macrophages (67%), while CD56+ NK cells were absent." (PMID 37509688, 2023). "In the TME, the expression of M1 markers MHC-II and CD86 is not affected by the presence of tumor cells, while the expression of M2-related markers CD206, CD163, and MerTK are markedly up-regulated in TC." (PMID 37345200, 2023). "In addition, by using dual IF staining, we confirmed that Gal-9 was mainly expressed in CD68+CD163+ KCs rather than tumor cells or M2 macrophages, indicating that Gal-9 may be involved in the formation of immune suppressive microenvironment in HBV-associated HCC." (PMID 35202002, 2022). "We found a remarkably higher proportion of CD163+ immune cells and FAP-positive fibroblasts in MRI true-positive tumor lesions compared with either MRI false-negative tumor lesions or benign tissue." (PMID 36874403, 2022). "We found that EMR1-TC was more correlated with CD68+/CD163+ TAMs than with CD3+/CD8+ tumor-infiltrating lymphocytes, and this relationship was more significant in the tumor center than in the tumor-invasive area (data not shown)." (PMID 36551877, 2022). "CD206 was significantly higher in TNBC tumours with PDLIM2-positive stroma than in those with PDLIM2-negative stroma, while CD163 was higher, but not quite reaching significance." (PMID 36531051, 2022). "Tumor densities of CD68+ and CD163+ cells were not different in C2D1 biopsies; neither those of DC-LAMP+, IDO1+, ICAM1+ or CD31+ cells (data not shown)." (PMID 35794623, 2022). "Mural nodules: polygon or spindle and giant tumor cells showed strong positive expression of cytokeratin (CK), epithelial membrane antigen (EMA), and vimentin (VIM), while CD163, S-100, Desmin, CD31, and MyoD1 were negative." (PMID 35836292, 2022). "Of interest, neither CD163 nor ALDH1A2 were detected in normal brain sections, suggesting that ALDH1A2 expression takes place within the GBM tumor microenvironment and is not a function of the non-diseased brain." (PMID 34572134, 2021). "Some M1 markers (IL1A, IL1B, CD86), M2 markers (CCL18, MRC1/CD206, CSF1R), and TAM markers (HLA-DR, IL1RN, CD163, ITGAM, SIGLEC1/CD169) were highly expressed on both tumor and non-tumor macrophages." (PMID 33918618, 2021). "Conversely, M2 macrophages express an abundant level of non-opsonic receptors (e.g., CD163, CD36, CD206), produce anti-inflammatory cytokines and contribute in many ways to tumor progression." (PMID 33924378, 2021). "Immunohistochemically, the tumor cells were negative for CD20, CD79a, CD3, CD5, c-kit, CD34, and TdT and positive for myeloperoxidase, CD33, CD68, and CD163." (PMID 34970464, 2021). "In this case, tumor cells were positive for desmin, αSMA, and h-caldesmon and negative for c-kit, S100, CD34, CAM5.2, EMA, CD163, and DOG1, supporting the diagnosis of PHL." (PMID 32648231, 2020).
tumor (continued). "AR was expressed in a median of 32.9% of CD163 and/or HLA-DRA and/or CD14 expressing cells in the Tumour area, which was not significantly different from cells in the tumour border or in the distant area (median 34.2% and 35.2%, respectively)." (PMID 32908142, 2020). "The markers of M2 macrophages (CD163, VSIG4, and MS4A4A) all showed significant negative correlation coefficient with ENDOU, implicating potential role of ENDOU in tumor infiltrating M2 macrophages." (PMID 33614471, 2020). "Immunohistochemistry study revealed that the tumor cells were positive for CD4 and CD30, and were negative for cytokeratin, CD3, CD20, CD68, CD163, lysozyme, ALK, S-100, and desmin." (PMID 32547956, 2020). "Immunohistochemical staining for tumor cells revealed desmin, α-smooth muscle actin (αSMA), and h-caldesmon to be diffusely positive, while c-kit, S100, CD34, CAM5.2, EMA, CD163, and DOG1 were negative." (PMID 32648231, 2020). "In the same cohort high CD163+/CD68+ ratio in the tumor front, but not in tumor stroma, was closely correlated with enhanced lymphovascular invasion, tumor invasion, and TNM stage as well as recurrence-free survival (RFS) and OS of patients with CRC." (PMID 33194645, 2020). "The change in macrophage markers at the TS interface was investigated using the mean expression of CD68, CD163 and CD206 of tumor (AE1AE3+) and non-macrophage (other) cells as baseline thresholds." (PMID 31477692, 2019). "The tumor cells were positive for CD68, NSE, S-100, and CD163 expression but negative for GFAP, Syn, and CD123 expression." (PMID 31023279, 2019). "CD68- and CD163-positive cells were not correlated with tumor size (CD68, P = 0.19; CD163, P = 0.27) or HER2 expression status (CD68, P = 0.33; CD163, P = 0.18)." (PMID 31528210, 2019). "Unlike tumor infiltrating T cells, CD68+, CD163+ TAMs and CD20+ TILs all failed to be prognostic indicators for OS and RFS." (PMID 30885276, 2019). "We detected a large number of CD14+ monocytes/macrophages with an alternative phenotype (CD64+CD163+) and CD4+ lymphocytes that infiltrated the tumour, but not the peritumour area." (PMID 30285662, 2018). "In contrast to the prevalence of CD163+ macrophages in tumor-bearing HSC-NOG-hIL-6 Tg mice, the frequency of CD163+ cells in intratumoral CD68+ cells was low in HSC-NOG non-Tg mice despite the small numbers of infiltrating human macrophages." (PMID 29456539, 2018). "The tumor cells showed generally positive for vimentin and negative for h-CALD, CD34, desmin, CD163, AE1/AE3, CK7 and CK20." (PMID 28320435, 2017). "By immunohistochemistry, the tumor cells are positive for histiocytic markers including CD68, CD163, CD11c and so on, whereas negative for S-100 protein and CDla." (PMID 27535029, 2016). "Immunostains were performed in which the viable adrenal cortical tumor cells expressed AE1/3 (weak, diffuse), melan A (strong, diffuse), and inhibin (moderate, diffuse), but were nonreactive for PAX8, CAIX, CD68, and CD163." (PMID 25108298, 2014). "We found that infiltration of CD163+ and CD68+ macrophages into tumor stroma, but not into tumor nest, were of clinical relevance." (PMID 22824040, 2012). "Lastly, CD163 was used as a single macrophage marker and does not capture the full macrophage landscape, and PET evaluation focused on SUVmax without assessing other metabolic parameters such as metabolic tumor volume (MTV) and total lesion glycolysis (TLG)." (PMID 41575920, 2026). "Higher expression of PD-L1, CD163, and SMA was detected in the tumor tissue than in the adjacent nontumor tissue, indicating that TAMs and fibroblasts may participate in the pathogenesis of RAH." (PMID 40416971, 2025). "Overall, CD163 GEX levels from bulk tissue correlated well with the four scoring categories of CD163 by IHC (density level none, low, medium and high) in tumor stroma at all sites (PT, LNM and DM)." (PMID 39751847, 2025).
tumor (continued). "Treatment with tumor secretions (TC group) altered several classical macrophage receptors/factors, including CD206, CD80, and CD163, in bone marrow-derived macrophages (macrophages φ, control group), and BAM15 treatment did not reverse tumor-induced macrophage differentiation (TC-BAM15 group)." (PMID 40595481, 2025). "The TAMs and lymphocytes had strong communication with the tumour cells in the responders, while in the non-responders, the cytotoxic CD8+ T-cells were in close proximity with immunosuppressive arginase 1 and CCR6 expressing CD163− TAMs." (PMID 38386105, 2024). "Moreover, CD163+ TAMs were positively correlated with LVI, again independent of their spatial location (tumor: q = 0.09; stroma: q = 0.06)." (PMID 38407373, 2024). "This study also provides the rationale for testing of this combination immunotherapy approach in the clinic, potentially in tumor types that do not respond to ICB and are characterized by high levels of collagen, TGF-β, or tumor-infiltrating CD163+ M2 macrophages." (PMID 35230974, 2022). "Our next objective was to investigate macrophage populations in the breast TMA by first analyzing the expression of CD14 (monocytes), CD68 (all macrophages), and CD163 (M2 macrophages), and further stratifying the expression of these markers within PDLIM2-positive and -negative tumours." (PMID 36531051, 2022). "CD163/FKBP51s+ monocytes decreased after surgery and almost disappeared during adjuvant TMZ, supporting the possibility that contrast agent enhancement of the lesion did not correspond to true tumor growth." (PMID 33917598, 2021). "Interestingly, the expression of macrophage markers in OPA appears to vary depending on their location within the affected tissue, with cells on the periphery of tumor foci being CD68 positive and cells within the tumor being CD163 positive and CD68 negative." (PMID 31434729, 2019). "In conclusion, both the CD163+ cells local infiltration and plasma sCD163 were of limited significance in HCC, and they were more likely markers related to active hepatitis rather than tumor progression." (PMID 23555776, 2013). "IHC was used to stain tumor tissues; however, because of the absence of some samples, ICOS levels were only determined in 47 patients, PD‐L1 levels were only measured in 62 patients, CD163 levels were only determined in 67 patients, and FOXP3 levels were only determined in 66 patients." (PMID 38616999, 2024). "However, the average number of communicating CD163+ TAMs has the advantage that this metric can be applied directly to histological images of any size (whole tissue, biopsy or TMA) without the need to select a tumor region of interest." (PMID 35053472, 2022). "On the other hand, the correlations of MIF scores with CD68, CD11c and CD163 scores in tumor nest and tumor stroma of NPC patients showed no statistical significance, suggesting that MIF may not directly affect to CD68, CD11c and CD163 in NPC." (PMID 34407796, 2021). "Interestingly, unlike CD68 and CD163, the expression of CD206 on each TAM population was not differential across the TS areas and only the CD68+CD206++ macrophages showed slightly increased expression within the tumor-nest." (PMID 31477692, 2019). "Interestingly, CD14−SIRPαlow cells exhibited properties of typical Mo/MΦs similar to CD14+SIRPαhi cells, but lacked CD163 expression, gained CD16 expression, migrated less and phagocytosed tumor cells less efficiently, yet stimulated rather than suppressed T-cell function." (PMID 31611550, 2019). "Total human CD11b+ myeloid cells were purified from the tumor or spleen of HSC-NOG-hIL-6 Tg mice or HSC-NOG non-Tg mice, as we could not obtain sufficient numbers of TAM-like cells when we gated HLA-DRlo/− IL-4Rα+ CD163+ CD68+ cells." (PMID 29456539, 2018).
tumor (continued). "Since the infiltration of CD163-positive cells into the tumor invasive front (CD163(IF)) but not the intra-tumor site (CD163(IT)) was strongly correlated with clinical outcomes (Overall survival [OS] and disease-free survival [DFS]) of the OSCC patients we present only the data of CD163 (IF) herein." (PMID 25461761, 2014).
cancer (406 papers, 2008 to 2026). A tumor composed of atypical neoplastic, often pleomorphic cells that invade other tissues. "An association has been established between heightened CD163+ macrophage density and a less favorable prognosis in patients with cervical, ovarian, breast, and bladder malignancies." (PMID 38730579, 2024). "The expression of specific biomarkers such as CD47, CD68, and CD163 is associated with these TAMs and has been studied extensively in relation to cancer prognosis." (PMID 39682556, 2024). "In several types of cancers, such as lymphoma, glioma, lung, gastric, thyroid, breast, and kidney cancers, high CD163 expression on TAMs has been associated with a worse prognosis." (PMID 38189834, 2024). "M2 macrophages are known to be involved in the aggressiveness of various cancers, and it was revealed that CD163 + in tumor associated macrophages (TAM) predict poor prognosis in cancer patients." (PMID 39327577, 2024). "But a high infiltration by CD163+ cells was associated with a lower cancer-specific survival (p=0.002) when compared to a low infiltration." (PMID 37435060, 2023). "While cytotoxic CD8+ T cells are well-established to correspond with beneficial outcomes, we were surprised to record a benefit of CD163+CD16a+ cells, since the CD163 marker is typically associated with M2 macrophages and poorer anti-cancer functions." (PMID 38318505, 2023). "We next analyzed additional markers such as FAPα, associated with CAFs (cancer-associated fibroblasts), and immune cell markers CD163, CD8 and PD-L1." (PMID 37596623, 2023). "Similar to the absolute number, high density of CD163+ MØs in the stroma or carcinoma nest were associated with poor outcome in patients with ESCC." (PMID 37254126, 2023). "Cox regression analysis revealed that a high CD163 content in cancer is anindependent prognostic factor associated with decreased overall survival." (PMID 36694901, 2022). "Cancer-associated fibroblasts and CD163+ M2-like TAMs correlated with the clinical prognosis of OSCC." (PMID 34041037, 2021). "The increased expression of CD163 was significantly associated with a poor prognosis in various cancers." (PMID 34837898, 2021). "CD163 positive cancer cells were significantly associated with shorter progression-free survival and lower overall survival." (PMID 34020650, 2021). "CM from both cancer cell lines induced mRNAs encoding the M2 markers CD163, FN1, and IL10 in ShCtrl THP-1 cells; the induction ranged from 2- to 4-fold by CM from MCF-7 cells, and from 5- to 60-fold by CM from MDA-MB-231 cells." (PMID 33086476, 2020). "At the same time, high number of CD163+ TAMs was associated with increasing cancer stage and the size of the residual site." (PMID 33194645, 2020). "In several types of cancers, such as lymphoma, glioma, lung, gastric, thyroid, breast, and kidney cancers, higher CD163 expression on TAMs has been associated with a worse prognosis." (PMID 32630659, 2020). "High level of CD163 was also associated with reduction of E-cadherin and high expression of vimentin in cancer cells, an indication of EMT." (PMID 33194645, 2020). "The macrophage-associated molecule CD163 has been reported to be a prognostic biomarker in different cancer types, but its role in CRC is still unclear." (PMID 32824692, 2020). "Macrophage phenotype in cancer cells, detected by CD163-expression, is suggested to be caused by fusion between TAMs and cancer cells." (PMID 29725763, 2018). "These markers and CD163 were also associated with poor overall survival, cancer invasion and worse clinical outcome." (PMID 29976244, 2018). "Later, its functional repertoire was expanded and significant associations of microvessel density with CD163 expression were demonstrated in several pathological conditions such as cancers." (PMID 29559970, 2018). "Further Multivariate analysis demonstrated that CD163 positive macrophages and cancer cells were potential risk factors for patients’ survival." (PMID 29152078, 2017).
cancer (continued). "It was interesting that elevated expression of CD163 in cancer cells was only associated with the depth of invasion, but not with histologic grade." (PMID 29152078, 2017). "Meanwhile, the expression of CD163 both in macrophages and in cancer cells was associated with poor overall survival and had a significant prognostic impact in OSCC." (PMID 26769084, 2016). "CD163 is regarded as a highly specific macrophage marker for M2 macrophages, and increased CD163 was significantly associated with a poor overall survival in cancers." (PMID 24883329, 2014). "Similarly, higher macrophage counts associated with cancer tissues when compared with borderline, interestingly, CD68 and CD163 touching cell counts, were significantly associated with malignant tumours." (PMID 38674108, 2024). "The increased expression of CD163 is associated with a poor overall survival in various cancers." (PMID 39065651, 2024). "This also suggests that CD163+ macrophages may compromise the bulk of precancer and cancer-associated macrophages." (PMID 37190121, 2023). "In many cancers, CD163+ cells (M2-type MΦ) have been associated with poor prognosis." (PMID 37435060, 2023). "Although the significance of CD163 in SCLC is unknown, many studies have demonstrated that CD163-positive TAMs are associated with a worse clinical course in many cancers." (PMID 36961655, 2023). "CD163 expression of TAMs has been linked to poor prognosis in a number of human cancers." (PMID 35418199, 2022). "CD163+ cancer cells were suggested to be caused via fusion between TAMs and cancer cells." (PMID 35847899, 2022). "In addition, the mRNA expression of CD163 is determined in the surgically resected malignant tumor tissues, which revealed that the mRNA expression of CD163 is significantly and negatively associated with survival rate." (PMID 32332633, 2020). "CD163 is the main marker on TAMs and is associated with a poor prognosis in patients with cancer." (PMID 32908942, 2020). "Likewise, in the current study, the mean number of cancer cells expressing CD163 was positively associated with MI, supporting a logical connection between fusion events and the number of TAMs." (PMID 29725763, 2018). "CD163-expression by cancer cells was significantly associated with MI and clinicopathological data." (PMID 29725763, 2018). "The investigation of CD163+ circulating M2-like monocytes as diagnostic biomarkers in breast cancer has suggested that they may have a role in reflecting cancer progression." (PMID 29885276, 2018). "Another TAM-associated factor, sCD163, could be a useful biomarker for cancer treatment, as it is an activation marker for CD163+ tissue macrophages that is present in the serum as a result of proteolytic shedding." (PMID 29410946, 2018). "We also found that CD163 could directly interact with CCL18 and CD86 which were associated with T-lymphocyte activation, indicating CD163 may be involved in cancer immunosurveillance." (PMID 29152078, 2017). "Importantly, the expression of CD163 in cancer cells was significantly associated with recurrence and mortality." (PMID 26769084, 2016). "CD163, a marker of M2 macrophages, has been studied in several aggressive tumors, and the increased expression of CD163 was significantly associated with a poor overall survival (OS) in various cancers." (PMID 24883329, 2014). "For predictive purposes, the optimal timing for assessing CD163 levels in tumor tissue is before the commencement of cancer treatment." (PMID 40075727, 2025). "The optimal timing for assessing CD163 as a predictive marker in cancer management is contingent on the specific clinical context and evaluation objectives." (PMID 40075727, 2025). "TAM subsets defined by surface markers, such as CD163+ and CD206+ macrophages, have distinct functional roles and are associated with different prognostic outcomes across multiple cancer types." (PMID 40936918, 2025).